CTLA4 (cytotoxic T-lymphocyte associated protein 4)
Diseases named in the same sentence as CTLA4 in open-access papers (continued):
Sharing a sentence is not in itself a finding about the gene and the disease.
prostate carcinoma (continued). "Additionally, since lactylation may regulate multiple immune checkpoints simultaneously, a multi-target approach combining anti-PD-1/PD-L1, anti-CTLA-4, and lactylation inhibitors may be necessary to overcome immune resistance in prostate cancer." (PMID 40535811, 2025). "Although CTLA-4 is not typically mutated in prostate cancer, its immunoregulatory functions indirectly support tumor progression by weakening anti-tumor immunity, promoting the release of pro-tumorigenic factors, and fostering a microenvironment conducive to angiogenesis, invasion, and metastasis." (PMID 41228234, 2025). "Further, a study showed that the gut microbiome plays a role on the therapeutic efficacy of prostate cancer immunotherapies —including cyclophosphamide and anti-PD-L1 therapies, and CTLA-4 blockade— and suggested that microbiome modulation may be a potential therapeutic strategy for prostate cancer." (PMID 38256945, 2024). "Also in the mouse model of prostate cancer, the combination of CTLA-4 antibody and cryoablation could effectively inhibit or slow down the growth of secondary tumors or induce tumor rejection." (PMID 36761748, 2023). "The VISTA protein is known as being responsible for the resistance to anti-PD-1/anti-CTLA-4 treatments, reported in prostate cancer, with an overall success rate of 30% of these targeted therapies, suggesting that blocking VISTA could be a good strategy to improve patients’ prognosis." (PMID 34771722, 2021). "Finally, a pilot phase 1 study (NCT03532217) is recruiting patients with metastatic castration-sensitive prostate cancer to investigate the effects of PROSTVAC in combination with a DNA vaccine encoding patient-specific neoantigens and checkpoint blockade (anti-CTLA-4 plus anti-PD-1)." (PMID 33008010, 2020). "Soluble T cell regulatory proteins CD28, CD80, CTLA4, and HVEM were correlated with both biochemical recurrence and progression risks in prostate cancer." (PMID 40659985, 2025). "Lastly, the effectiveness of checkpoint inhibitors in prostate cancer, such as PD-L1, PD1, and CTLA-4 inhibitors, have been very poor despite multiple attempts to exploit these agents in prostate cancer." (PMID 40647555, 2025). "Previous studies have reported that 4-1BBL-expressing tumor vaccine in combination with CTLA-4 blockade was effective in reducing tumor incidence and increasing in the survival of C57BL/6 mice transplanted subcutaneously with prostate cancer RM-1 cells." (PMID 39624845, 2024). "In the clinical prediction of different treatment regimens for prostate cancer anti-PD1 and anti-CTLA4, the low CHMP4C expression group always showed better response compared to the high CHMP4C expression group." (PMID 37388224, 2023). "For instance, in prostate cancer bone metastases CTLA-4 is highly evident but infiltrating T cells are scarce; therefore, anti-CTLA-4 (ipilimumab) is one such drug strategy that is being used to revitalize immune cell attraction to the tumor." (PMID 35455987, 2022). "We then used a Kaplan–Meier survival model to depict the differences between high and low expression of three markers (CTLA4, OX40L, and CD11c) and their effects on the time to biochemical relapse for prostate cancer patients." (PMID 36230846, 2022). "During the treatment of patients with prostate cancer with anti-CTLA-4 antibodies, an increase in VISTA expression was also detected, accounting for the resistance of anti-CTLA-4 therapy." (PMID 35463322, 2022). "Attempts have been made with the anti-CTLA-4 antibody ipilimumab plus radiation therapy, ADT and other checkpoint inhibitors (anti-PD-1), although with limited enhanced treatment effects in prostate cancer." (PMID 33786638, 2021). "In the mouse model of bone metastasis of prostate cancer, the combination therapy of RANKL inhibitor and CTLA-4 inhibitor decreased the activity of osteoclasts and skewed bone remodeling toward osteoblastic activities." (PMID 34877360, 2021).
prostate carcinoma (continued). "This approach was tested in a murine model of prostate cancer, in which TRAMP mice were treated with the cellular vaccine GVAX (a cellular vaccine made from gene-modified tumor cells), anti-CTLA-4 blocking antibody, or the combination." (PMID 33008010, 2020). "CTLA-4 blockade was first evaluated in prostate cancer in the transgenic adenocarcinoma of the mouse prostate (TRAMP) model, where the role of adjunctive CTLA-4 blockade in mice with minimal residual metastatic disease was studied." (PMID 32630247, 2020). "To model therapy for advanced prostate cancer, we treated robustly established tumors (≈ 450 mm3) with combination therapy using JQ1 and CTLA4 IgG2a." (PMID 31653272, 2019). "Taken together, these data demonstrate the activity of anti-CTLA-4 and BET bromodomain inhibition in a murine prostate cancer model." (PMID 31653272, 2019). "In this study, we evaluated this interesting approach for CTLA4 enhancement on prostate stem cell antigen (PSCA)-specific immune responses and its anti-tumor effects in a prostate cancer mouse model." (PMID 27783810, 2016). "Resveratrol induces growth arrest through activation of FOXO transcription factors in prostate cancer cells and suppresses the immune response through CD28/CTLA-4 and CD80 co-stimulatory pathways." (PMID 25501752, 2014). "Ipilimumab, a monoclonal antibody blocking the immune checkpoint CTLA-4, has recently been evaluated in two randomized, Phase III, placebo-controlled trials in men with metastatic, castrate-resistant prostate cancer." (PMID 23557194, 2013). "We used a well-described genetically engineered mouse (GEM), autochronous prostate cancer model (Pro-TRAMP) to explore the relative sequencing and dosing of anti-CTLA-4 antibody when combined with a cell-based, GM-CSF-secreting vaccine (GVAX)." (PMID 23557194, 2013). "Beyond CTLA-4, additional inhibitory immune receptors such as LAG-375, TIM-376, and VISTA, may also be regulated by lactylation in prostate cancer." (PMID 40535811, 2025). "PRAD ranks as the primary cause of mortality among men, and inherently exhibits resistance to ICBs, and neither monotherapy targeting anti-PD-1/PD-L1 nor anti-CTLA-4 demonstrates a significant impact on the overall survival of prostate cancer patients." (PMID 39120585, 2024). "Metastatic prostate cancer immune infiltrate lacks PD1, PD-L1 and CTLA4." (PMID 38850363, 2024). "However, high immune-refractory rates have been observed in the prostate cancer with use of single-agent ICB, even when combinational treatment with CTLA-4." (PMID 37880708, 2023). "Conversely, ongoing efforts are evaluating the efficacy of combining CTLA-4 and TGF-β inhibitors against castrate-resistant prostate cancer in mice, citing decreased bone metastasis growth and T regs, while increasing Th1; findings the researchers expect to advance into clinical application." (PMID 35455987, 2022). "Therapy with anti-CTLA-4 monoclonal antibodies has been investigated in both phase I/II trials, as well as two notable phase III trials in the setting of advanced prostate cancer—one in chemotherapy-naïve patients and the other in patients that had disease progression while on docetaxel." (PMID 33820953, 2021). "Together, the prior evidence of limited efficacy of CPI monotherapy in treating prostate cancer and the promising preclinical data for dual CPI therapy have led to multiple clinical trials involving dual anti-CTLA-4 and anti-PD-1/PD-L1 CPI therapy for the treatment of mCRPC." (PMID 33820953, 2021). "In support of this hypothesis, a recent report described the use of TH-302 in prostate cancer models and showed that, by using the HAP to target hypoxia, T cell infiltration was increased and sensitivity to CTLA-4 and PD-1 blockade was restored." (PMID 33910023, 2021).
prostate carcinoma (continued). "However, in a murine preclinical model of prostate cancer, mice who received GVAX prior to anti-CTLA-4 demonstrated increased CD8+ and CD4+ T cells compared to those who received anti-CTLA-4 treatment first." (PMID 33019493, 2020). "In addition, spontaneous prostate cancer in TRAMP transgenic mice, which is entirely checkpoint blockade resistant, responded dramatically to combination CTLA-4/PD-1 blockade when co-administered with the hypoxia-reducing agent TH-302." (PMID 30400822, 2018). "In this regard, a large multiple-center trial showed that combined radiation and anti-CTLA-4 blockade (ipilimumab) did not result in significant clinical benefits in 799 prostate cancer patients." (PMID 27835902, 2016). "Cytotoxic T lymphocyte antigen-4 (CTLA-4) blockade was showed to induce a larger number of antibody responses in the clinical responders than non-responders in patients with prostate cancer." (PMID 26788323, 2016). "Patients with CRPC (n = 28) received thirteen intradermal administrations of Prostate GVAX, consisting of two allogeneic GM-CSF-transduced and irradiated prostate cancer cell lines (LN-CaP and PC3) and six infusions of escalating doses of anti-CTLA4/ipilimumab." (PMID 26196012, 2014). "In addition anti-CTLA-4 monotherapy, trials are ongoing with anti-CTLA-4 (ipilimumab) combined with ProstVac-VF or a GM-CSF-secreting whole tumor cell vaccine (GVAX; BioSante Pharmaceuticals) in prostate cancer." (PMID 24216992, 2013). "Thus, as clinical trials have shown, targeting CTLA4 or PD-1 alone will not succeed in treating prostate cancer." (PMID 32552802, 2020). "Although anti-CTLA-4 is not currently FDA-approved for the treatment of advanced prostate cancer, a randomized Phase III trial showed a trend towards increased survival, suggesting that this agent may have some clinical activity." (PMID 31653272, 2019). "Moreover, CTLA-4 blockade induced a broader antibody response in prostate cancer patients who responded to therapy compared with non-responders." (PMID 26788324, 2016). "At this moment, no ICIs have been approved for prostate cancer, and most clinical trials, including a phase III study with ICIs, CTLA-4 and PD-1/PD-L1 inhibitors, are disappointing." (PMID 33060772, 2020).
ovarian carcinoma (142 papers, 2013 to 2026). A malignant neoplasm originating from the surface ovarian epithelium. "The diagnostic worth of the serum levels of pd-1, pd-l1, and CTLA-4 among patients with ovarian cancer was evaluated." (PMID 39456930, 2024). "IPS expression in the low-risk group receiving CTLA-4, PD-1, and CTLA-4 combined with PD-1 treatment was significantly higher than that of the high-risk group, suggesting ovarian cancer." (PMID 39478854, 2024). "The combination of olaparib and tremelimumab (anti-CTLA-4) was tolerable in recurrent BRCA-associated ovarian cancer, with preliminary results showing evidence of therapeutic effect." (PMID 36831435, 2023). "Using a BRCA1-deficient ovarian cancer mouse model, PARPi was shown to increase the therapeutic effects of CTLA-4 blockade which, as a single therapy, had limited benefit." (PMID 36831435, 2023). "Regarding ovarian cancer, CTLA-4 expression has a positive impact on OS and is associated with prolonged survival." (PMID 35054356, 2022). "Tumor-intrinsic STING signaling facilitates BRCA-1 mutated ovarian cancer cells’ resistance to both PD-L1 and CTLA-4 therapies by upregulating VEGF-A." (PMID 36189283, 2022). "In particular, therapy aimed at the programmed cell death 1 (PD-1) and the cytotoxic T-lymphocyte associated antigen 4 (CTLA-4) pathways are currently being studied in numerous clinical trials in ovarian cancer." (PMID 31091744, 2019). "Anti-CTLA-4 synergizes with PARPis in a BRCA-deficient ovarian cancer model and the combination treatment improves mice survival." (PMID 30487462, 2018). "In our study, the expression patterns of genes associated with anti-CTLA-4 therapy, anti-PD-1/PD-L1, and TILs were highly consistent: all genes were highly expressed in type I and II ovarian cancer." (PMID 32793247, 2018). "In preclinical combination studies, CTLA-4 blockade has been shown to synergise with PARP inhibition in Brca1-deficient mouse models of ovarian cancer in a manner dependent on IFN-γ secretion into the TME." (PMID 29123260, 2018). "In a mouse model of ovarian carcinoma, neutralization of CTLA4 signals caused regression of growing tumors, however, only in an early tumor stage." (PMID 28275576, 2017). "The ovarian cancer environment caused migration of CTLA4+ FOXP3+ GITR+ Tregs via the chemokine CCL22, secreted by tumor cells and TAMs, and its receptor CCR4, expressed by infiltrating Tregs." (PMID 28275576, 2017). "Higuchi looked at CTLA-4 blockade with PARPi ABT-888(Veliparib) in BRCA1-deficient murine ovarian cancer models and showed that combination CTLA-4/PARPi was able to provide therapeutic benefit in these experiments supporting further clinical investigations." (PMID 27231574, 2016). "In addition, NETs also mediated resistance to immune checkpoint blockade PD-1 and cytotoxic T-lymphocyte associated protein 4 (CTLA4) by Ovarian cancer in pancreatic cancer." (PMID 36993957, 2023). "Thus, this study shows the benefits of blending PARPis and anti-CTLA-4 to treat BRCA-deficient ovarian cancer." (PMID 30487462, 2018). "PD-1/PD-L1 and CTLA-4 inhibitors enhance antitumor immunity across gynecological cancers, with high ORRs in PD-L1-positive cervical tumors, microenvironment modulation in ovarian cancer, and novel combinations overcoming resistance in endometrial cancer." (PMID 41029427, 2025). "For example, dual inhibition of PD-1 and CTLA-4 has yielded durable survival benefits in several solid tumors, and similar patterns have begun to emerge in ovarian cancer trials." (PMID 41293268, 2025). "In ovarian cancer, the tumor microenvironment promotes immune suppression via CTLA-4, impairing tumor-infiltrating lymphocytes (TILs)." (PMID 41029427, 2025). "Beyond anti-PD-1 therapy, epidrugs like decitabine demonstrate synergy with anti-CTLA-4 in epithelial ovarian cancer, as evidenced by orthotopic mouse models using the BR5FVB1-Akt cell line." (PMID 41029427, 2025).
ovarian carcinoma (continued). "Ovarian cancer, highly lethal, benefits from PD-1/PD-L1 and CTLA-4 inhibitors targeting the immunosuppressive microenvironment." (PMID 41029427, 2025). "With the rapid development of PD-1/PD-L1, CTLA-4, oncolytic viruses, cancer vaccines, adoptive cell therapy, etc., tumor immunotherapy has provided new opportunities for the treatment of ovarian cancer." (PMID 39981173, 2025). "A phase II trial of ipilimumab (anti-CTLA-4) and nivolumab (anti-PD-1) in 17 patients with rare non-epithelial ovarian cancers reported a 25% ORR in granulosa cell tumors, with one CR and one PR lasting over four Years, And a 50% clinical benefit rate." (PMID 41029427, 2025). "Currently, only a few early-phase clinical studies (phases 1 and 2) have investigated anti-LAG-3 monoclonal antibodies (mAbs) as monotherapy or in combination with other ICIs such as anti-PD-1 and anti-CTLA-4 in advanced solid tumors, including ovarian cancer." (PMID 41383608, 2025). "Immunophenotypic scores (IPS) of ovarian cancer patients were subsequently used to predict their responsiveness to anti-CTLA4 therapy." (PMID 40612060, 2025). "The first generation of PD-1/PD-L1 and CTLA-4 immune checkpoint inhibitors was only sensitive in a subset of patients and has limited efficacy in treating ovarian cancer." (PMID 38634058, 2024). "To evaluate the response of ovarian cancers in different risk groups to immune checkpoint inhibitors (ICIs), we calculated the IPS score (including CTLA4 blocker and PD-1/PD-L1/PD-L2 blocker) was much significantly higher in the low-risk group patients." (PMID 38925650, 2024). "Low risk score indicated a lower immune escape score, TIDE score, and higher PD1&CTLA4 immunophenoscore in ovarian cancer." (PMID 37851341, 2023). "Utilizing the PTGS2/CTLA4 ratio, we stratified samples into high- and low-expression groups based on the median ratio to evaluate the impact on survival in multiple ovarian cancer cohorts." (PMID 38201508, 2023). "This work represents the first evidence of the influence of COX-2 on NK cell function as a crucial element in the efficacy of anti-CTLA-4 therapy for ovarian cancer patients that exhibited high tumoral levels of CTLA-4." (PMID 38201508, 2023). "A randomized phase 2 trial assessed the combination of the CTLA-4 inhibitor ipilimumab with the PD-1 inhibitor nivolumab compared to nivolumab alone in recurrent ovarian cancer." (PMID 38248092, 2023). "In recent years, immunotherapies such as immune checkpoint inhibitors have developed rapidly and have been investigated for the maintenance treatment of ovarian cancer, including anti-PD-1/PD-L1 and anti-CTLA-4." (PMID 37424730, 2023). "The results suggested that ovarian cancer with low risk score had a higher CTLA4 IPS, PD1 IPS and CTLA4/PD1 IPS (all p<0.05)." (PMID 37851341, 2023). "Combining CTLA-4 blockade with the demethylating agent decitabine in a murine ovarian cancer model led to elevated differentiation of naïve into effector T cells, extended responses of cytotoxic lymphocytes, and prolonged mouse survival." (PMID 36975506, 2023). "One of the more promising results for treating ovarian cancer was discovered by combining a PD-1/CTLA-4 dual blockade with the adoptive transfer of autologous TILs in humanized PDX-ovarian cancer models." (PMID 37376049, 2023). "Most studies to date describing immunotherapy for ovarian cancer have focused on molecules such as PD-1, PD-L1 and CTLA-4." (PMID 36359346, 2022). "Classical PD-1, PD-L1, and CTLA-4 inhibitors have made great progress in the treatment of ovarian cancer." (PMID 36311734, 2022). "In summary, as our study demonstrates, PD-1, PD-L1, and CTLA-4 can be used to help during the diagnostics of ovarian cancer." (PMID 35054356, 2022). "Only PD-1 is expressed at high levels in CD103+ CD8+ TRM cells in ovarian cancer, and the expressions of CTLA-4, Tim-3 and LAG-3 are negligible." (PMID 36077846, 2022).